ZNF507 (zinc finger protein 507)
Description:
May be involved in transcriptional regulation.
Synonyms: KIAA1084; Zfp507
Tractability: PROTAC: ubiquitination databases record sites on it.
Gene: Protein-coding gene on chromosome 19 (32,345,594 to 32,387,667, forward strand). Ensembl gene ENSG00000168813.
Subcellular location: Nucleus
Subcellular location (Human Protein Atlas): Nucleoli; Cytosol
Gene Ontology:
Molecular function: DNA-binding transcription factor activity; transcription cis-regulatory region binding
Biological process: regulation of DNA-templated transcription
Cellular component: nucleus
Genetic constraint (gnomAD): Loss-of-function variants: 22 observed, 68.04 expected, observed/expected ratio (o/e) 0.32, 90% interval 0.23 to 0.46. The upper end of that interval is the gene's LOEUF score, 0.46, which puts it in group 2 of 6, group 1 being the genes least tolerant of losing a copy. Missense variants: 975 observed, 1,066.3 expected, observed/expected ratio (o/e) 0.91, 90% interval 0.87 to 0.96. Synonymous variants: 413 observed, 393.48 expected, observed/expected ratio (o/e) 1.05, 90% interval 0.97 to 1.14.
Homologues: Orthologues: chimpanzee ZNF507 (99% identical), macaque ZNF507 (97% identical), dog ZNF507 (90% identical), rabbit ZNF507 (89% identical), pig ZNF507 (89% identical), rat Zfp507 (80% identical), mouse Zfp507 (80% identical), tropical clawed frog znf507 (50% identical), zebrafish znf507 (45% identical). Paralogues in human: ZNF777 (12% identical), ZNF407 (11% identical), ZNF408 (11% identical), ZBTB17 (10% identical), ZNF17 (10% identical), ZNF398 (10% identical), WIZ (10% identical), ZNF34 (10% identical), ZNF416 (10% identical), ZNF287 (10% identical), ZNF333 (10% identical), ZNF530 (10% identical), and 38 more.
Diseases named in the same sentence as ZNF507 in open-access papers:
ZNF507 is named in the same sentence as 9 diseases in open-access papers, as found by Europe PMC text mining. Sharing a sentence is not in itself a finding about the gene and the disease. The quoted sentences say what the papers report.
prostate carcinoma (3 papers, 2021 to 2024). A carcinoma that arises from epithelial cells of the prostate gland. "In prostate cancer (PC), ZNF507 expression was associated with metastatic PC with a high grade." (PMID 39273015, 2024). "The SATB1 gene can contribute to tumor growth in a mammary adenocarcinoma mouse model, while ZNF507 was reported to affect TGF-β signaling to promote prostate cancer." (PMID 35625741, 2022).
schizophrenia (2 papers, 2020 to 2021). A major psychotic disorder characterized by abnormalities in the perception or expression of reality. "Similar to ZNF507, TGF-β and its related immune activity has been linked to schizophrenia, suggesting an interaction in neurodevelopmental disorders." (PMID 34537073, 2021).
prostate adenocarcinoma (1 paper, 2021). "Interestingly, since there was no significant survival rate difference in prostate adenocarcinoma (PA) patients who showed high or low ZNF507 expression, considerably higher ZNF507 level was observed in recurrent PC tumors." (PMID 34537073, 2021).
cancer (2 papers, 2021 to 2024). A tumor composed of atypical neoplastic, often pleomorphic cells that invade other tissues. "We identified several TFs, including GTF2I, NFIB, NFATC4, ZNF37A, KLF13, and ZNF507, involved in cancer metastasis." (PMID 39273015, 2024). "As there was a limitation of in vivo metastasis models that injecting tumor cells intravenously does not perfectly recapitulate the metastatic cascade, they were sufficient to prove the physiological changes in cancer properties by ZNF507 knockdown." (PMID 34537073, 2021). "For these reasons, in addition to further studying ZNF507 gene in other cancers, studies on ZNF507 and TGF-β signaling in early and neurodevelopment are highly recommended." (PMID 34537073, 2021). "Studies of genetic variations in cancer have indicated that ZNF507 may be relevant in several cancers." (PMID 34537073, 2021). "However, the precise role of ZNF507 in the cancer remains unclear." (PMID 34537073, 2021).
tumor (2 papers, 2021 to 2022). "Our in vivo experimental studies, which displayed alteration of tumor growth and metastatic capacity affected by ZNF507 knockdown, also support this hypothesis." (PMID 34537073, 2021).
brain disorder (1 paper, 2022). A disease affecting the brain or part of the brain. "Identifying these targets could be key in determining what impact, if any, ZNF507 has on various brain disorders." (PMID 35100360, 2022).
neurodevelopmental disorder (1 paper, 2021). A behavioral and cognitive disorder with onset during the developmental period that involves impaired or aberrant development of intellectual, motor, or social functions. "Various studies have implicated ZNF507 as a risk factor for neurodevelopmental disorders and the early development." (PMID 34537073, 2021).
ZNF507 also shares sentences with these, for which no sentence is quoted: mammary adenocarcinoma (1 paper); myocardial infarction (1).